EPHB4 (EPH receptor B4)
Diseases named in the same sentence as EPHB4 in open-access papers (continued):
Sharing a sentence is not in itself a finding about the gene and the disease.
gastric cancer (6 papers, 2020 to 2026). A primary or metastatic malignant neoplasm involving the stomach. "Functionally, EPHB4 promoted lymphatic metastasis in vivo and enhanced migration and invasion of gastric cancer cells in vitro." (PMID 42222600, 2026). "The up-regulation of BC005927 enhances EPHB4 expression, which in turn promotes gastric cancer metastasis under hypoxic conditions." (PMID 40861273, 2025). "Specifically, HIF-1α interacts with hormone response elements (HREs) within the promoter region of lncRNA BC005927, inducing the oncogenic role of lncRNA BC005927 in gastric cancer through the upregulation of the EPH receptor B4 (EPHB4)." (PMID 38339408, 2024). "EPHA1, EPHA2, EPHA3, EPHA5, EPHB2 and EPHB4 expression has been reported as 2-fold higher in stromal cells isolated from gastric cancer tissues compared with normal gastric tissue stromal cells." (PMID 34445116, 2021). "Similar to the classical interactive mode between HIF-1α and miRNAs, HIF-1α can also directly interact with the HREs in the lncRNA BC005927 promoter region, inducing lncRNA BC005927 to play its oncogenic role in gastric cancer by upregulating EPH receptor B4 (EPHB4)." (PMID 32014012, 2020). "EPHB4 is located 300 kb upstream of BC005927, and its expression is positively correlated with that of BC005927 in gastric cancer tissues." (PMID 40861273, 2025).
lymph node metastasis (6 papers, 2012 to 2025). "More recently, EphB4 expression was correlated with differentiation, lymph node metastasis and TNM stage in 28 NSCLC patients, while the polymorphism in EphB4 at rs314310 appeared to correspond to protein expression and disease susceptibility." (PMID 24495444, 2014). "The circulating EphB4 mRNA was closely correlated with the histopathological type (p = 0.032) while the circulating EGFR mRNA was closely correlated with the lymph node metastasis (p = 0.023)." (PMID 27827952, 2016). "EphB4 and its sole ligand EphrinB2 are overexpressed in all primary and metastatic tumors, with EphB4 overexpression correlating with advanced stage disease and lymph node metastasis." (PMID 22523710, 2012). "Furthermore, we found that EphB4 expression was related to OSCC differentiation, lymph node metastasis, clinical stage, and prognosis." (PMID 34539874, 2021).
lymphedema (6 papers, 2020 to 2025). Excess fluid collection in tissues, causing swelling. "Previously, late-onset lymphedema was associated with only a few EPHB4 variants." (PMID 38820174, 2024). "The EphrinB2/EphB4 signaling pathway has been identified as a promising target for the treatment of lymphedema and related diseases." (PMID 40766782, 2025). "The diminished signaling between EphrinB2 and EphB4 in lymph vessels mirrors the heightened vessel leakage evident in response to bacterial infections and primary lymphedema." (PMID 40766782, 2025). "Last, it is of note that in some families with EPHB4 mutations, affected individuals in different generations present only with lymphatic abnormalities, i.e., LRHF or lymphedema." (PMID 37259315, 2023). "Inherited inactivating mutations in EPHB4 and RASA1 are also responsible for the development of lymphatic vascular abnormalities in humans, including lymphedema, chylous ascites and chylothorax, lymphatic-related hydrops fetalis, central conducting lymphatic anomaly, and abnormal lymphatic flow." (PMID 35015735, 2022). "For EPHB4, these include lymphatic-related hydrops fetalis (LRHF, accumulation of fluid in the fetus because of lymphatic dysfunction), central conducting lymphatic anomaly (a lymphatic vessel flow disorder) and lymphedema (tissue edema consequent to lymphatic dysfunction)." (PMID 37259315, 2023).
endometrial cancer (5 papers, 2005 to 2022). Primary or metastatic malignant neoplasm involving the endometrium (mucous membrane that lines the endometrial cavity). "Several reports have examined concomitant expression of the ligand EFNB2 and its receptor EphB4 in leukemia-lymphoma cell lines, and in endometrial cancer." (PMID 21333016, 2011). "A positive correlation between histological grade, stage of carcinoma and level of EphB4 protein has also been reported in breast and endometrial carcinoma." (PMID 16171530, 2005). "Lenvatinib in combination with golvatinib (E7050; c-Met, Tie2, and EphB4 inhibitor) reduced the CD31+ endothelial network, SMA+ pericyte network, and disrupted pericyte-mediated vessel stabilization, decreasing the interaction between ECs and pericytes in thyroid and endometrial cancer models." (PMID 34209679, 2021).
fetal hydrops (5 papers, 2016 to 2025). "NGS analysis highlighted the c.2231G>A (p.Arg744His) variant in EPHB4, which has been classified as likely pathogenic based on previous associations in two cases of fetal hydrops and experimental functional evaluation for causality (source: NCBI)." (PMID 40259928, 2025). "EphB4 mutations are known to cause hydrops fetalis due to the role of EphB4 in the development of lympho-venous valves." (PMID 31782728, 2019). "Independent exome sequencing projects on 2 families with a history of in utero and neonatal deaths associated with nonimmune hydrops fetalis uncovered 2 heterozygous missense variants in the gene encoding Eph receptor B4 (EPHB4)." (PMID 27400125, 2016). "The phenotype of EPHB4 has high intra‐ and interfamilial variability and can be associated with a spectrum of phenotypes ranging from subtle features of lymphatic dysfunction to lethal nonimmune hydrops fetalis." (PMID 41317105, 2025).
lung adenocarcinoma (5 papers, 2015 to 2022). A carcinoma that arises from the lung and is characterized by the presence of malignant glandular epithelial cells. "The results of our present study can contribute to the development of effective therapeutic strategies for osimertinib in EGFR mutation-positive lung adenocarcinoma cases by focusing on the characteristics of EphB4 as a predictor of the therapeutic effects of osimertinib and as a prognostic factor." (PMID 34445227, 2021). "Therefore, in this study, we examined the association between EphB4 and cell proliferation both in vitro and in immunohistochemical studies using human lung adenocarcinoma tissues." (PMID 34445227, 2021). "Immunohistochemical studies using human lung adenocarcinoma demonstrated that the EphB4 status in carcinoma cells was positively correlated with tumor size, T factors, and Ki-67 LI, all of which represented increased cell growth ability." (PMID 34445227, 2021). "In the present study, we analyzed both mRNA and protein expression of EphB4 in CRLCs from clinical specimens of lung adenocarcinoma, and all samples revealed persistent EphB4 expression." (PMID 32733636, 2020). "We also studied the clinicopathological significance of EphB4 in 84 lung adenocarcinoma patients." (PMID 34445227, 2021). "Furthermore, knockdown of EphB4 has been reported to suppress the cell proliferation of lung adenocarcinoma cell lines, and knockdown of EphA2 has been reported to improve gefitinib sensitivity in gefitinib-resistant lung adenocarcinoma cell lines." (PMID 34445227, 2021). "Osimertinib can exert stronger growth inhibitory effects in NSCLC patients with a high expression of EphB4 than in those with a low expression of EphB4, and it may improve the prognosis in EGFR mutation-positive lung adenocarcinoma patients." (PMID 34445227, 2021). "In addition, EphB4 had a significantly negative impact on the prognosis/clinical outcome in EGFR mutation-positive lung adenocarcinoma patients." (PMID 34445227, 2021). "Furthermore, EphB4 turned out to be a significant poor prognostic factor in EGFR mutation-positive lung adenocarcinoma patients but not in EGFR mutation-negative patients." (PMID 34445227, 2021). "Therefore, we hypothesized that the lower impact of EphB4 on cell proliferation in EGFR mutation-negative lung adenocarcinoma could be due to the potential influence of various other factors related to smoking." (PMID 34445227, 2021). "EphB4 has been reported to be a poor prognostic factor in NSCLC and lung adenocarcinoma patients." (PMID 34445227, 2021).
malignant mesothelioma (5 papers, 2019 to 2023). A malignant neoplasm of the pleura or peritoneum, arising from mesothelial cells. "In particular, we demonstrate that EphB4 protein expression in malignant mesothelioma cells depend upon a degradation rescue mechanism controlled by the autocrine IGF-II-insulin receptor-A specific signaling axis." (PMID 31270394, 2019). "EphB4 is an oncogenic tyrosine kinase receptor expressed in malignant mesothelioma as well as in a variety of cancers." (PMID 31270394, 2019). "We recently found IGF-II to be a key driver of protein EphB4 ectopic expression in malignant mesothelioma cells and we identified a ubiquitin/UPS-associated post-transcriptional mechanism tightly regulating EphB4 protein degradation/stabilization." (PMID 31810288, 2019). "Altogether, these findings disclose a novel molecular mechanism for the maintenance of EphB4-expression in malignant mesothelioma cells and other IGF-II-secreting cancers (IGF2omas)." (PMID 31270394, 2019). "Ultimately, our study showing the dependency between the autocrine IGF-II -generated stimuli and the steady-state EphB4 protein expression in cancer suggests an underscored role for this novel degradation rescue mechanism as a potential player in the tumorigenic switch in malignant mesothelioma." (PMID 31270394, 2019). "However, under such cultural conditions (hypoxic, serum-containing and growth-factor rich), the neutralization of secreted IGF-II was able to significantly downregulate EphB4 as well as VEGF-A suggesting a major role for IGF-II as a mediator of HIF effects in malignant mesothelioma cells." (PMID 31270394, 2019). "In malignant mesothelioma cells, upon autocrine IGF2 stimulation, IR-A phosphorylates EphB4 at tyrosine 987, thus maintaining EphB4 steady-state levels." (PMID 34440844, 2021). "In order to verify whether the observed co-expression trend in EphB4 and autocrine IGF-II in cancer cell lines was functionally correlated, we set up an experiment using three IGF-II secreting malignant mesothelioma cell lines (NCI-H28, NCI-H2052, and MSTO-211H)." (PMID 31270394, 2019).
neuroblastoma (5 papers, 2017 to 2025). Neuroblastoma (NB) is the most common solid, extracranial childhood tumor. "EPHB4 was identified as a tumorigenic factor, with EPHB4 gain correlating with advanced-stage neuroblastoma and poor overall survival (OS)." (PMID 38612645, 2024). "Additionally, using a survey set of patient-derived neuroblastoma samples and osteosarcoma samples, we observed an overall strong incidence of EphB4 and EphrinB2 expression in both tumor types." (PMID 28817624, 2017). "Finally, our expression data for EphB4 and EphrinB2 may indicate that further study of the EphB4 and EphrinB2 receptors in neuroblastoma and osteosarcoma could be warranted." (PMID 28817624, 2017). "Considering the differential expression of EphB4 and EphrinB2 between the aRMS and eRMS, we decided to investigate whether EphB4 and EphrinB2 were expressed in other pediatric solid tumors, particularly neuroblastoma and osteosarcoma." (PMID 28817624, 2017). "As for neuroblastoma, low EPHA2 expression can discriminate the N-type from the S-type, which is characterized by high EPHA2 expression, while low EPHB4 levels are typical in embryonal rhabdomyosarcoma." (PMID 38612645, 2024). "In neuroblastoma, EphB4 and CLDN1 are not expressed, but in addition to LAT1, some ROBO1 is expressed." (PMID 40076777, 2025).
synovial sarcoma (5 papers, 2016 to 2022). "EphB4 mRNA and protein expression were upregulated in synovial sarcoma patients and in vitro blockade of EphB4 using either siRNA approaches or the specific EphB4 kinase inhibitor NVP-BHG712 inhibited cell proliferation and cell migration." (PMID 34440844, 2021).
colorectal tumors (4 papers, 2006 to 2024). "On the other hand, contrary findings show that the expression of EPHB4 is often reduced or lost in colorectal tumors." (PMID 38651144, 2024). "Furthermore, a pattern of inactivation similar to EPHB2 has been observed for EPHB4 and EPHB3 in colorectal tumors and/or cell lines, respectively." (PMID 16740153, 2006).
mesothelioma (4 papers, 2013 to 2023). A usually malignant and aggressive neoplasm of the mesothelium which is often associated with exposure to asbestos. "We shed light on the molecular machinery associated with autocrine IGF-II regulation of oncogenic EphB4 kinase expression in a previously characterized IGF-II+/EphB4+ Mesothelioma cell line." (PMID 37108544, 2023). "Here we show that EphB4 expression in malignant mesothelioma cells is markedly decreased upon neutralization of cancer-secreted IGF-II." (PMID 31270394, 2019). "EphB4 was overexpressed in 72% of mesothelioma tissues evaluated, with 85% of epithelioid and 38% of sarcomatoid subtypes demonstrating overexpression." (PMID 23721559, 2013). "This is in agreement with earlier studies in mesothelioma cell lines in which knockdown of EphB4 was shown to reduce cellular motility and invasiveness in addition to proliferation." (PMID 23844053, 2013). "Xenograft tumors established with human mesothelioma cells were treated with an EphB4 inhibitor (monomeric soluble EphB4 fused to human serum albumin, or sEphB4-HSA)." (PMID 23721559, 2013). "Our search for IGF-II signal-dependent EphB4 interactors focused on MSTO211H cells among the three histological types recapitulating previously studied mesothelioma cell lines which displayed the highest dependence of EphB4 protein levels from the degradation rescue signal provided by IGF-II." (PMID 37108544, 2023). "We investigated EphB4 expression in 39 human mesothelioma tissues by immunohistochemistry." (PMID 23721559, 2013). "Importantly, we have also shown that EphB4 is expressed in mesothelioma and provides a survival advantage to tumor cells." (PMID 23721559, 2013). "We also found that the EphB4-Ephrin-B2 inhibitor sEphB4-HSA, alone or combined with the anti-VEGF antibody Bevacizumab was highly active in inhibiting mesothelioma growth in xenograft models." (PMID 23721559, 2013). "EphB4 angiogenic kinase over-expression in Mesothelioma cells relies upon a degradation rescue signal provided by autocrine IGF-II activation of Insulin Receptor A. However, the identity of the molecular machinery involved in EphB4 rapid degradation upon IGF-II signal deprivation are unknown." (PMID 37108544, 2023).
metastatic disease (4 papers, 2012 to 2025). "In metastatic disease, both proteins are associated with organ-specific metastasis development, depending on the expression of both Ephrin-B2 and EphB4 on tumor- and organ-specific endothelial cells." (PMID 34360793, 2021). "Finally, we identified the EPHs (EPHA2, EPHA4, EPHA8, and EPHB4) and EFNs (EFNA1, EFNA3, EFNA4, and EFNB2) that are significantly overexpressed in the aggressive epithelioid histological subtype and revealed that the majority of EPHs/EFNs are overexpressed in metastatic disease." (PMID 41516312, 2025).
osteoporosis (4 papers, 2020 to 2022). A condition of reduced bone mass, with decreased cortical thickness and a decrease in the number and size of the trabeculae of cancellous bone (but normal chemical composition), resulting in increased fracture incidence. "The glucocorticoid-induced osteoporosis mouse model causes down-regulation of EphB4 in osteoblasts and up-regulation of ephrin-B2 in osteoclasts." (PMID 33634116, 2021). "EphB4-ephrin-B2 expression is also dysregulated in a diabetes-related osteoporosis model." (PMID 33634116, 2021).
pancreatic cancer (4 papers, 2016 to 2025). "The total EphB4 expression was also seen to be higher in pancreatic cancer; however, relatively lower expression in the normal pancreas." (PMID 34298619, 2021). "In particular, we demonstrated that EphB4 is highly activated in pancreatic cancer PDXs and is amenable to targeting with different agents, including antibodies and small-molecule kinase inhibitors." (PMID 34298619, 2021). "Overall, these results indicate that EphB4 is a promising target for pancreatic cancer treatment that needs to be explored further." (PMID 34298619, 2021). "Based on in vivo mice experiments using human serum albumin-conjugated soluble EphB4, it was confirmed that EphB4 could serve as a potential therapeutic target in pancreatic ductal adenocarcinoma and further research is necessary to prove its efficacy in the treatment of pancreatic cancer patients." (PMID 34298619, 2021). "Immunoprecipitation of tyrosine-phosphorylated proteins followed by immunoblotting using anti-EphB4 showed high expression of EphB4 in 7/13 of the PDX samples, indicating EphB4 hyperphosphorylation in pancreatic cancer." (PMID 34298619, 2021). "The most promising approach inhibiting this interaction so far involves a soluble EphB4 ECD conjugated to human serum albumin (EphB4-ECD-HSA), this has shown anti-angiogenic effects on pancreatic tumours in Rip1-Tag2 mice, which could be improved with Dll4-Notch blockade using Dll4-ECD-Fc." (PMID 26620208, 2016).
Parkes Weber syndrome (4 papers, 2023 to 2025). "The search for the causal gene mutation can be carried out (mutations of the RASA1 and EPHB4 genes, identified respectively in CM-AVM type 1, which includes Parkes-Weber syndrome, and CM-AVM type 2)." (PMID 39885577, 2025). "Cutaneous vascular lesions are a common hallmark of developmental vascular disorders such as RASA1- and EPHB4-mutated CM-AVM25,27, ENG1- and ACVRL1-mutated HHT29, and RASA1-mutated Parkes Weber syndrome, among others." (PMID 37978175, 2023). "Notably, recent studies have identified mutations in RASA1 and EPHB4 in CM-AVM and Parkes Weber syndrome, respectively, highlighting the potential utility of genetic testing in complex cases." (PMID 40357088, 2025).
medulloblastoma (3 papers, 2020 to 2025). A malignant, invasive embryonal neoplasm arising from the cerebellum. "Among medulloblastoma cell lines, EphB4 expression was higher in DAOY and UW-426, whereas Res-256 exhibited minimal basal phosphorylation." (PMID 41200151, 2025). "Similar to EphB3, EphB4 expression is downregulated in migratory medulloblastoma cells, suggesting an inverse relationship with invasion and a possible association with stem-like tumor phenotypes." (PMID 41200151, 2025). "This pattern suggests a potential link between EphB4 and Sonic Hedgehog signaling, although its precise role in medulloblastoma biology remains to be defined." (PMID 41200151, 2025). "Microarray profiling of 29 medulloblastomas, validated in an additional cohort of 60 tumors, revealed that EphB4 is predominantly expressed in SHH-subtype tumors, with minimal expression in non-SHH variants." (PMID 41200151, 2025). "Regarding EPH/ephrin members’ expression, upregulation of EPHB2 and ephrin-B1 has been reported in tumor samples compared to normal cerebellum, while EPHA2, EPHB2, and EPHB4 showed overexpression in medulloblastoma cell lines." (PMID 38612645, 2024). "EphB2 and its ligand ephrin-B1 have been shown to be highly expressed in medulloblastoma tissue samples, and EphA2, EphB2, and EphB4 are overexpressed in medulloblastoma cell lines." (PMID 33050158, 2020).
Oral Squamous Cell Carcinoma (3 papers, 2021 to 2025). "The Ephrin type-B receptor 4 (EPHB4), a receptor tyrosine kinase, is notably overexpressed in oral squamous cell carcinoma (OSCC), and this overexpression correlates with poor prognosis, making EPHB4 a broadly relevant target in HNSCC and a promising candidate for CAR-T cell therapy." (PMID 40647513, 2025).
osteosarcoma (3 papers, 2017 to 2024). A usually aggressive malignant bone-forming mesenchymal neoplasm, predominantly affecting adolescents and young adults. "EPHB4-CAR-T cells demonstrated potent and sustained killing activity against tumor cells, including RMS, osteosarcoma, and triple-negative breast cancer cell lines." (PMID 33816783, 2021).